CELF1 (CUGBP Elav-like family member 1)
Diseases named in the same sentence as CELF1 in open-access papers (continued):
Sharing a sentence is not in itself a finding about the gene and the disease.
tumor (continued). "We next hypothesized that misexpression of CELF1 would impact tumour cell colonization in an in vivo xenograft model of experimental metastasis via tail-vein injection." (PMID 27869122, 2016). "We hypothesize, that if these CELF1 controlled mRNAs were important for tumor formation and/or progression, OHKC-CELF1 cells would have distinct relative mRNA and splice variant expression levels in comparison to control OHKC cells." (PMID 26498364, 2015). "Finally, we provide evidence that reduction of CELF1 protein using a xenograft tumorigenesis mouse model decreased tumor growth." (PMID 26498364, 2015). "The RNA binding protein, CUGBP Elav-like family member 1 (CELF1) binds to mRNAs to regulate splicing, translation, and decay and may thereby have a role in translational activation of epithelial-mesenchymal transition genes that drive tumour progression." (PMID 38329136, 2024). "Interestingly, both STIP1-CREB3L1 and CELF1-DDIAS were identified in the same tumor (case 1)." (PMID 28186972, 2017). "In addition, CELF1 mRNA was elevated in tumor samples in comparison to normal tissues." (PMID 26498364, 2015). "Thus, CELF1 is a critical regulator of tumor cell biological processes." (PMID 26498364, 2015). "Hence, a potent pharmacological intervention disrupting the CELF1-mRNA interfaces could abrogate tumor cell growth." (PMID 26498364, 2015). "Interestingly, and in contrast to our previous results in a human cell-derived xenograft model, we found that induction of CELF1 knockdown and rescue with any of our three variant proteins had no impact on the kinetics of growth of a primary tumor derived from 4T1 cell implantation." (PMID 39343007, 2024). "Genetic epistasis experiments confirmed that these PKCs function upstream of CELF1 in this EMT program, and CELF1 phosphorylation impacts tumor metastasis in a xenograft model." (PMID 39343007, 2024). "In breast epithelial cells, CELF1-OE promoted the translation of epithelial to mesenchymal transition (EMT) and ultimately tumor progression." (PMID 35287612, 2022). "Our data present an 11-component genetic pathway, invisible to transcriptional profiling approaches, in which the CELF1 protein functions as a central node controlling translational activation of genes driving EMT and ultimately tumour progression." (PMID 27869122, 2016). "To determine if CELF1 protein expression affected tumor growth in vivo, we created UMSCC-74B cells stably transduced with inducible control or CELF1 shRNA vectors." (PMID 26498364, 2015). "Our previous study determined that CELF1 protein and mRNA expression was elevated in HNSCC tumor samples compared to adjacent normal tissues." (PMID 26498364, 2015). "Aberrant splicing events of CELF1 can lead to the production of abnormal isoforms, contributing to the translational activation of genes that drive epithelial–mesenchymal transition (EMT) and, consequently, tumor progression." (PMID 41306913, 2025). "Correlation analysis of the alternative splicing events of CD44 with expression levels of CELF1 and ELAVL1 based on RNA-Seq data from TCGA revealed that high expression of CELF1 and/or ELAVL1 is correlated with the inclusion of CD44 variable exons in eight tumor types." (PMID 38106992, 2023).
heart disease (3 papers, 2015 to 2022). "Mice with a four- to eight-fold increase in CELF1 levels in the heart died within two weeks from severe cardiac disease due to dilated cardiomyopathy and degeneration of cardiomyocytes." (PMID 34769305, 2021). "However, neither the rapidity and severity of disease in these mice, nor the levels of increased CELF1, are typical of cardiac disease in DM1 patients." (PMID 34769305, 2021).
infection (1 paper, 2013). The state of being infected such as from the introduction of a foreign agent such as serum, vaccine, antigenic substance or organism. "Infection of cells with lentivirus containing CELF1 shRNA significantly reduced CELF1 gene and protein expression levels in both A549 and H1299 cells." (PMID 24237593, 2013). "The survival rate of CELF1 knockdown cells was markedly (P < 0.0001) reduced at the 5th day of infection compared with the non-infected and control siRNA infected A549 and H1299 cells." (PMID 24237593, 2013).
neurological diseases (1 paper, 2021). "Besides that, in this LD block, several variants act as eQTLs/sQTLs in the brain and whole blood, altering the expression of many genes already related to LOAD or other neurological diseases in human or animal studies, such as CELF1 itself, MADD, MYBPC3, NR1H3, NUP160, SPI1, and TOMM40." (PMID 34291080, 2021).
skeletal muscle disorder (1 paper, 2018). A disease involving the skeletal muscle tissue. "The role of CELF1 in the DM1-related heart and skeletal muscle disorders has been shown in short-lived mouse models overexpressing Celf1." (PMID 29716962, 2018).
CELF1 also shares sentences with these, for which no sentence is quoted: myopathy (6 papers); Atrophy (3); Brain atrophy (2); breast tumor (2); hypertrophy (2); Intellectual disability (2); leukemia (2); myotonic dystrophy type 2 (2); neuroblastoma (2); neurogenic muscle atrophy (2); adenocarcinoma of the lung (1); Anxiety (1); astrocytoma of the brain (1); cardiac arrhythmia (1); dementia (1); epilepsy (1); esophageal cancer (1); esophageal squamous cell carcinoma (1); glioblastoma (1); head and neck squamous cell carcinoma (1); hepatoblastoma (1); hyaline fibromatosis syndrome (1); Insulin resistance (1); invasive ductal breast carcinoma (1); lamb syndrome (1); metastatic melanoma (1); muscle atrophy (1); neuromuscular disease (1); oculopharyngeal muscular dystrophy (1); Parkinson’s (1).
A further 10 diseases each share a sentence with CELF1 in 1 paper.